ERBB2 (erb-b2 receptor tyrosine kinase 2)
Diseases named in the same sentence as ERBB2 in open-access papers (continued):
Sharing a sentence is not in itself a finding about the gene and the disease.
breast cancer (continued). "Trastuzumab is a monoclonal antibody specific for ErbB2, which when coupled with chemotherapy significantly improves outcome of early stage HER2+ breast cancer patients." (PMID 23408142, 2013). "In breast cancers, RAS is often activated by HER2 [ErbB2/epidermal growth factor receptor (EGFR) 2/Neu] receptor tyrosine kinase and is over expressed and persistently activated in approximately 25 % of cancers." (PMID 24147022, 2013). "In fact, trastuzumab (Herceptin®) is a monoclonal therapeutic antibody against breast cancer that targets erbB-2 by interacting with the CR2 domain, thus preventing erbB-2 dimerisation." (PMID 24386251, 2013). "We observed that ErbB2-mediated breast tumorigenesis is enhanced by LKB1 deletion, which is consistent with both experimental and clinical data linking LKB1 to breast cancer." (PMID 24280377, 2013). "In breast cancer, PGC-1α has been shown to promote the growth of ERBB2+ tumors in vivo and to regulate their mitochondrial metabolism and angiogenic properties." (PMID 24304688, 2013). "Consistent with the ErbB2 mouse model of breast cancer, we observed a positive correlation between low Her2 mean fluorescence intensity (MFI) levels and breast cancer cell lines with quantifiable asymmetric segregation of template DNA (P = 0.02)." (PMID 24238140, 2013). "In previous studies, the authors state that a fraction of human breast cancers and cat mammary lesions show a good correlation between high expression levels of ERBB2 mRNA and the erbB-2 protein." (PMID 24386251, 2013). "Concerning the determination of breast cancer prognosis, it has recently been suggested that the quantification of ERBB2 mRNA transcripts by qRT-PCR should be applied to the routine erbB-2 IHC procedures as an additional molecular test." (PMID 24386251, 2013). "In breast carcinoma, a relationship between CB2 expression, the histological grade of the cancer, and other markers of prognostic and predictive value, such as ErbB2/HER-2 oncogene, oestrogen, and progesterone receptors, has been reported." (PMID 24369462, 2013). "Two human breast carcinoma cell lines, MCF7 and BT474, were used to evaluate the ErbB2-targeted imaging in vitro." (PMID 24069396, 2013). "A report showed that ErbB2/HER2 and ErbB3/HER3 were both targets of miR-125b in breast cancer SKBr3 cells." (PMID 22523546, 2012). "In breast cancer cells, for example, using DNA fibers hybridized with genomic probes, we detected high-level amplification not only of MYC but of ERBB2, as well." (PMID 22580498, 2012). "Lastly, we document that PADI2 expression is highly correlated with HER2/ERBB2 overexpressing and luminal subtype breast cancers." (PMID 23110523, 2012). "Recently, two studies showed that PTPMeg2 promotes dephosphorylation of EGFR and ErbB2 thereafter to impair the activation of STAT3 and STAT5 in breast cancer cells." (PMID 22394684, 2012). "RNA-seq data from a collection of 57 breast cancer cell lines was queried for PADI2 levels, and correlations with known subtype and HER2/ERBB2 status were evaluated." (PMID 23110523, 2012). "The majority of triple transgenic females that overexpressed wildtype ErbB2 developed CK8-positive, luminal-type mammary tumors after a medium latency of more than 6 months in the FVB background (data not shown)." (PMID 22952764, 2012). "Human epidermal growth factor receptor 2 (ErbB-2/HER2), one of the members of the ErbB family of membrane receptor tyrosine kinases, is a major player in the breast cancer scenario." (PMID 22356700, 2012). "Regarding FGFR4, a previous study has shown that it is over-expressed in a significant fraction of HER2+ breast cancer samples and simultaneous inhibition of FGFR4 and ERBB2 using small molecule inhibitors have synergistic anti-proliferative effect." (PMID 22343619, 2012).
breast cancer (continued). "Thus, we hypothesized that the synergy between decrease PTPN13 and increased ErbB2 activation that drives tumor growth and invasion is mediated via EphrinB1 and, further, that EphrinB1-mediated signaling is enhanced in breast cancers with compromised PTPN13 expression." (PMID 22279592, 2012). "Several studies have shown that ERBB2/HER2 and the basal or TNBC subtypes of breast cancer are the predominant types of breast cancer that metastasize to the brain." (PMID 23118876, 2012). "Comparative qPCR of ER+ and ERαKD cell lines was performed on a sample of relevant genes (ErbB2, BRCA1, PR, and of course ERα) to verify if the specific knockdown of ERα affected the expression of other breast cancer-related genes." (PMID 23140372, 2012). "Another high scoring upregulated network identified ERBB2, an important membrane bound receptor tyrosine kinase, as the nodal molecule and is known to crosstalk with NFkβ and PI3K-Akt to promote breast cancer." (PMID 23216862, 2012). "Specifically, the breast cancer line BT-474 (EC50 56.4±13.8 μM) expresses high levels of ErbB3 and ErbB2 and exhibits ligand-independent ErbB3 activation." (PMID 23166750, 2012). "Previously we determined a subline of the aggressive breast cancer cell line MDA-231 efficiently colonizes mouse bone after intracardiac inoculation, expresses high levels of EGFR protein and modest levels of the ErbB2 and ErbB3 receptors, and sheds AREG." (PMID 22276166, 2012). "As expected, the classic known breast cancer amplicons were the most common, including the CCND1 amplicon at 11q13 in 18 tumors, the ERBB2 amplicon at 17q12 in 17 tumors followed by 8p12 and 20q amplicons in 11 tumors." (PMID 23186559, 2012). "In the last decade, genomic studies have identified five breast cancer intrinsic subtypes (Luminal A, Luminal B, HER2 (overexpressing the ERBB2), basal-like and claudin-low)." (PMID 23158001, 2012). "We also observed that angiotensin receptor type 1 (AGTR1) and ERBB2 are the nodal molecules in ninth and tenth IPA network and has relevance to breast cancer." (PMID 23216862, 2012). "We first visualized, by western-blot analysis, the presence of ErbB2, EGFR and Met in mammary tumor lysates obtained from different mice." (PMID 23028720, 2012). "Moreover, ErbB-2 is able to co-localize with the cyclin-dependent kinase p34Cdc2 in both the cytoplasm and the nucleus, and subsequently phosphorylate it, leading to resistance to taxol treatment in breast cancer, suggesting that ErbB-2 functions as a kinase in the nucleus." (PMID 22520625, 2012). "We describe a complex consisting of ErbB2, Src, EphrinB1 and PTPN13 that mediates EphrinB1 phosphorylation and downstream signaling in breast cancer cells." (PMID 22279592, 2012). "Comparative studies have also shown that chemically-induced mammary carcinomas, as with their human counterparts, have altered TGFB, erbB2, and cyclin D1 expression." (PMID 23508728, 2012). "Another classic example of a typical cancer outlier gene is ERBB2/HER-2, an important therapeutic target over-expressed in about 20% of human breast cancers." (PMID 21365010, 2011). "We further examined the effect of EGCG on erbB2/Her2 employing HNSCC and breast cancer cell lines, and found that EGCG can inhibit the erbB2/Her2 activation, demonstrating the first example of erbB2/Her2 inhibition by EGCG in human malignancies." (PMID 21274257, 2011). "As a result, human breast cancers have been subclassifed into four reproducible subtypes: luminal A (LUM A), luminal B (LUM B), ERBB2-amplified (HER2+), and basal-like." (PMID 21858162, 2011). "Known therapeutic targets for breast cancer, such as ESR1, ERBB2 (HER2) and ERBB3 (HER3), are identified as showing bimodality in their gene expression level in breast cancer." (PMID 22053771, 2011). "Two notable factors are the ErbB2 (HER2/neu) and 14-3-3ζ proteins, both of whose overexpression has been correlated with poor clinical prognoses of breast cancer patients." (PMID 21647371, 2011).
breast cancer (continued). "This phenomenon was confirmed by comparison of the breast cancer cell lines MCF-7, which has low ErbB2 levels, and SK-BR-3, which highly overexpresses the receptor." (PMID 21609478, 2011). "In vivo, AST1306 potently suppressed tumor growth in ErbB2-overexpressing adenocarcinoma xenograft and FVB-2/Nneu transgenic breast cancer mouse models, but weakly inhibited the growth of EGFR-overexpressing tumor xenografts." (PMID 21789172, 2011). "Although research into the role of ErbB receptor signalling in breast cancer has focused primarily on EGFR and ErbB2, it is becoming increasingly clear that both ErbB3 and ErbB4 also have important roles to play in this disease." (PMID 21396094, 2011). "In addition, further experiments are required to explore whether the mechanisms of lapatinib-induced cell death in leukemia are different than the mechanisms that kill cancer cell lines that die in much lower concentrations, such as breast cancer cells with higher levels of ErbB2 expression." (PMID 22216158, 2011). "Along the same lines, ErbB2 and IGF-1R heterodimers contributed to trastuzumab resistance in breast cancer cells." (PMID 22216158, 2011). "We have applied the criteria used for scoring of ERBB2 immunohistochemistry in breast cancer to obtain standardised assessment of expression and hence a more rational prediction of the proportion of bladder cancer patients who may benefit from ERBB2-targeted therapy." (PMID 21364580, 2011). "Lapatinib is a very potent inhibitor of ErbB-2 activity in vitro; however, lapatinib alone reduced tumour growth by only 40% in our BT474 model of ErbB-2-positive breast cancer." (PMID 21847123, 2011). "Genomics has revealed at least four subtypes of breast cancer: luminal A, luminal B, basal, and HER2/ERBB2-overexpressing." (PMID 22044691, 2011). "Trastuzumab (Tzb and Herceptin) was the first immunotherapeutic drug for the treatment of breast carcinomas overexpressing the HER2 (erbB-2) oncogene that was successful; however, the mechanisms that could explain de novo and acquired resistance to anti-HER2 monoclonal are not well understood." (PMID 22295229, 2011). "HER2 (ErbB2) is a surface protein and member of the epidermal growth factor receptor (EGFR) family that is overexpressed in approximately one-fifth of breast cancers." (PMID 21203579, 2010). "Also, with the prevalence of both oncogenes overexpressed in human breast cancer, it is important to investigate their interaction in mammary tumorigenesis to determine whether it would be useful to combine therapeutics directed at both ErbB2 and IGF-IR." (PMID 20825649, 2010). "The activation of ErbB2 recruits cSrc and FAK, resulting in the phosphorylation of cSrc at Tyr 216 and FAK at Tyr 861 in breast cancer cells." (PMID 21034468, 2010). "It has been observed that ErbB2 overexpression can alleviate the requirements of IGF and EGF for proliferation in a series of human normal and breast cancer cell lines." (PMID 20825649, 2010). "The best established genes with bimodal frequency distributions in breast cancer are the estrogen receptor (ESR1) and erbB2." (PMID 20500820, 2010). "An IGF-IR inhibitor was even found to enhance ErbB2-mediated apoptosis in a human breast cancer cell line with very little IGF-IR expression; evidence of this inhibitor augmenting the suppression of ErbB2 phosphorylation was also discovered." (PMID 20825649, 2010). "An ErbB2 inhibitor Tyrphostin (AG825) abolishes the ethanol-stimulated interaction between ErbB2 and FAK, as well as the adhesion of breast cancer cells to the ECM." (PMID 21034468, 2010). "This is intriguing because of the large body of work linking ERBB2, PTEN and PI3-kinase signaling to breast cancer." (PMID 20712882, 2010). "Meaburn and Misteli analyzed the radial distribution of four genes related to cell survival, mobility and migration, namely AKT1, VEGF, ERBB2, and FGFR1 in a cell-model of breast cancer." (PMID 20958983, 2010).
breast cancer (continued). "The expression profiles of many of the known breast cancer gene markers such as ESR1, ERBB2 and AR have been shown to follow a strong bimodal distribution, which corresponds to different tumour subtypes." (PMID 21152022, 2010). "The epidermal growth factor (EGF) receptor gene (EGFR/HER1/ERBB1) and other EGF receptors (HER2/NEU/ERBB2, HER3 and HER4) are frequently expressed in human breast cancer cells, including MDA-MB-231 cells." (PMID 21029421, 2010). "In mammary cancer cohort mice treated with vehicle and fed HFD, we found two solid nodular ERBB2-positive tumors with zonation." (PMID 20435547, 2010). "Overexpression of the related receptor, ErbB2, in MCF-7 breast carcinoma cells resulted in enhanced NFκB activation in response to ionizing radiation." (PMID 21203561, 2010). "HER2/Neu/ErbB2 is a member of the epidermal growth factor receptor (EGFR) family that is amplified and overexpressed in 20%–30% of breast carcinomas." (PMID 21113302, 2010). "This subset included known breast cancer genes, like EGFR (7p11), FGFR1 (8p12), ERBB2 (17q12), PPM1D (17q23) and ZNF217 (20q13)." (PMID 19582160, 2009). "A recent study reported that the gene expression profile associated with insulin-like growth factor treatment of MCF7 cells contained significant overlap with gene signatures derived from breast cancer cell lines that over-expressed EGFR and ERBB2." (PMID 19552798, 2009). "In this report, we examined the relationships between ERBB2, AP-2α, and YY1 both in breast cancer tissue specimens and in a mammary cancer cell line." (PMID 18218085, 2008). "The GRB7 gene also co-amplifies with additional genes located within the ERBB2 amplicon such as CAB1, A39, C51 and MLN64 in gastric and breast cancers." (PMID 19424485, 2008). "Co-amplification of ERBB2 and GRB7 was also found in human breast cancer cell lines, and has been additionally detected in non-invasive ductal carcinomas in situ." (PMID 19424485, 2008). "Based on the antiproliferative profile in breast cancer cell lines, it is difficult to link NVP-AUY922 antitumor activity with a specific genetic marker such as ERBB2 expression or ER status." (PMID 18430202, 2008). "Ras signal transduction pathways play an important role in breast cancer progression, as evidenced by the frequent over-expression of the Ras-activating epidermal growth factor receptors EGFR and ErbB2." (PMID 18597688, 2008). "It targets ERBB2 and ERBB3 in human breast cancer cell lines and its depletion is critical for the proliferation of differentiated cells." (PMID 18478077, 2008). "EGFR signaling is frequently altered in breast cancer, where EGFR and ErbB2 over-expression are common events." (PMID 18597688, 2008). "ErbB2, a member of the epidermal growth factor receptor (EGFR) family, is overexpressed in 20% to 30% of human breast cancer cases and forms oncogenic signalling complexes when dimerised to ErbB3 or other EGFR family members." (PMID 18700973, 2008). "We first detected levels of ERBB2, AP-2α, and YY1 proteins by immunohistochemistry (IHC) in tumor specimens from 55 cases of breast carcinomas." (PMID 18218085, 2008). "One of these markers is the HER2 antigen (also called HER-2, ERBB2, p185HER-2), which is overexpressed in a wide variety of human neoplasms, particularly in ovarian and breast carcinomas." (PMID 18560598, 2008). "In the present study, we investigated the activation of the NF-κB transcription factor in breast cancer in terms of ER signalling and the hyperactivation of MAPK due to EGFR and/or ErbB2 overexpression, with special emphasis on the IBC phenotype." (PMID 17700572, 2007). "In a set of 317 primary breast cancers patients with known clinical outcome (STB data set), we evaluated E2F1 mRNA expression levels with respect to other proliferation markers, ER and ERBB2 status and clinical outcome." (PMID 17535433, 2007).
breast cancer (continued). "Changes in copy numbers of genes such as ERBB2 and c-MYC have been extensively documented in breast cancer and are present in model cell lines." (PMID 16417655, 2006). "The finding of the c-kit expression of breast cancer is quite a contrast to the finding of EGFR and erbB2 expression of breast cancer, in which the overexpression of EGFR and erbB2 indicated a malignant phenotype of breast cancer." (PMID 16721362, 2006). "Among them, ErbB2 (or HER-2/neu) amplification strongly correlates with steroid receptor negative tumors, and amplification of AIB1(amplified in breast cancer 1) gene is prevalent in estrogen receptor (ER) positive tumors." (PMID 16670003, 2006). "Gene amplification and over-expression of the HER-2/neu gene, also known as c-erbB-2 or ERBB2, is frequently observed (approximately 25–30%) in human breast cancer." (PMID 16420697, 2006). "Chromosomal amplifications have been described in breast cancer for several genes, including MYC at 8q24 and ERBB2 at 17q11.2." (PMID 16168117, 2005). "Western blot analyses were used to determine erbB2 and erbB3 protein expression in tumor-derived cell lines (and the control SKBR-3 human breast cancer cell line)." (PMID 16168116, 2005). "We further tested the relationship between ErbB-2 expression and the expression of UCHL1, CPS1 and copine III in a panel of breast cancer cell lines." (PMID 14710226, 2004). "To analyse the molecular mechanisms leading to ERBB2 overexpression in non-breast cancer cell lines, we transfected four LUCIFERASE reporter vectors containing 200 bp–6 kb fragments of the ERBB2 promoter in colon and ovary cell lines." (PMID 12942124, 2003). "Mimotopes for a receptor tyrosinekinase gene were also selected using a breast cancer SKBR-3 cDNA phage display library,screened against an anti-erbB2 monoclonal antibody." (PMID 18628851, 2002). "In TCGA-BRCA and GSE22820 breast cancer cohorts, P4HA2 expression positively correlated with ERBB2." (PMID 41424847, 2026). "Comparing to Srsf3 WT liver cancer, Srsf3 KO significantly increases Sox4, E2f1, Trpv4, Trim6, and Myc expression, but does not so in Erbb2 breast cancer." (PMID 40568073, 2025). "Most basal breast cancers are TNBC, but there is also an ERBB2-amplified basal subtype." (PMID 40457074, 2025). "In conclusion, our analyses demonstrated that HER2E tumors in ERpHER2n early breast cancer are neither driven by ERBB2 alterations nor predominantly constituted by HER2-low tumors." (PMID 40044693, 2025). "The overexpression/amplification of human erb-b2 receptor tyrosine kinase 2 (ERBB2 or HER2), a member of the epidermal growth factor receptor family, is observed in 15–20% of breast cancers and is predictive in the treatment response of its targeted therapeutic agents." (PMID 39107524, 2025). "A Phase II clinical trial (NCT01792050) investigated the efficacy of combining Indoximod with the taxane chemotherapy drug Docetaxel in treating metastatic ERBB2-negative breast cancer patients." (PMID 39973065, 2025). "Triple-negative breast cancer, a heterogeneous subtype characterized by the absence of estrogen, progesterone, and ERBB2 (formerly HER2) receptor expression, accounts for approximately 15% of all breast cancer cases." (PMID 40373794, 2025). "Among females of all ages and races and ethnicities, there was no statistically significant change in the incidence rates of HR-negative and ERBB2-negative (triple-negative) breast cancer, but considerable variation by age and race and ethnicity was observed." (PMID 39853979, 2025).